INS (insulin)
Diseases named in the same sentence as INS in open-access papers (continued):
Sharing a sentence is not in itself a finding about the gene and the disease.
depression (continued). "A repeated measures ANOVA model did not reveal any significant effects of depression or anxiety on the time course of glucose, insulin or C-peptide during the oral glucose tolerance test after correction for weight and physical activity." (PMID 25642391, 2015). "Adjusting for insulin sensitivity (HOMA-%S) and hs-C reactive protein attenuated these associations, but depression and CVD risk did not." (PMID 26167206, 2015). "Further, abnormalities in blood glucose control and insulin sensitivity are seen in patients with major depressive disorder, even in individuals who are non-obese and not diabetic." (PMID 26231223, 2015). "According to the literature, there is little evidence that depression is a plausible side effect of insulin, biguanides, and/or sulfonylurea." (PMID 26457080, 2015). "Chronic dysregulation of the HPA axis, such as in depression, can lead to chronically increased serum levels of cortisol, which can have negative effects on insulin and blood glucose levels." (PMID 26231223, 2015). "1,389 participants completed the Edinburgh Depression Scale (EDS) in 2005 and were followed until: 1) insulin therapy was started, 2) death, 3) an oral antihyperglycemic drug (OAD) prescription gap >1 year, 4) last OAD prescription in 2010 or 5) the end of the study (December 31, 2010)." (PMID 24223860, 2013). "People with depression were not more likely to start insulin therapy earlier or later than their non-depressed counterparts (HR = 0.98, 95% CI 0.66–1.45), also after adjustment for sex and age (HR = 0.95, 0.64–1.42)." (PMID 24223860, 2013). "In the same way, type 2 diabetic patients who evidenced current depression had higher rates of insulin use than those without depression (27.8% vs. 8.8%; p = 0.04)." (PMID 21978660, 2011). "Patients with T2DM who had depression had a poorer glycemic control compared to patients without mood disorder, even after controlling for age and insulin use." (PMID 21978660, 2011). "This idea is corroborated by the finding that patients who remained on an oral regimen had the lowest depression scores at baseline as well as at follow-up, although their negative appraisal of insulin treatment increased." (PMID 20920319, 2010). "Compared to adults without depression, those with depression had lower incomes, more comorbid conditions (10.2 vs. 6.5, p < 0.05), and were more likely to use insulin (18.7% vs. 7.3%, p < 0.01)." (PMID 17442110, 2007). "However, our unique contribution is the emphasis on the statistically significant relationship between insulin use and depression in patients with good GC, a topic that has not been explored in previous research." (PMID 40429455, 2025). "However, the metabolic effects of apelin (increasing insulin sensitivity, glucose uptake, thermogenesis, and normalising lipid profile) are without a doubt beneficial in depression’s pathophysiology." (PMID 41375608, 2025). "Key confounders such as depression, anxiety, and medication use (e.g., insulin, sedatives, antidepressants) were not accounted for in this study, which may have influenced both glycemic control and sleep outcomes." (PMID 41190157, 2025). "Therefore, our interpretation of the relationship between insulin use and depression, independent of glycemic control, should be considered with caution." (PMID 40429455, 2025). "While atypical depression is categorized based on symptom presentation, IMD specifically refers to a depression subtype characterized by concurrent immunometabolic dysregulations, including low-grade inflammation, altered insulin signaling and metabolic disturbances." (PMID 41436766, 2025). "While previous studies have reported a higher prevalence of insulin therapy in patients with moderate to severe depression, our data do not allow us to definitively conclude whether this relationship is independent of HbA1c levels." (PMID 40429455, 2025).
depression (continued). "Markers such as fasting insulin, HOMA-IR, leptin/adiponectin ratio, and high-sensitivity C-reactive protein (hs-CRP) may help identify patients with metabolic-inflammation-driven subtypes of depression or bipolar disorder." (PMID 41010364, 2025). "However, there was a significant interaction between depression and no longer meeting PTSD criteria and risk of starting insulin." (PMID 39136942, 2024). "IN-insulin did not affect any of the other parameters measured for cognition, gait, or depression." (PMID 36429060, 2022). "However, the pattern of change was similar among those with and without a history of depression in that glycemia and insulin resistance improved overall over the 2 years in both groups." (PMID 35084637, 2022). "However, we found no mediation by weight, depression, androgens, insulin, HOMA-IR, cortisol or oligomenorrhea." (PMID 35581616, 2022). "In addition, research on insulin and depression is no longer limited to traditional perspectives such as nutrient metabolism, monoamine neurotransmitters, and HPA axis." (PMID 34366917, 2021). "In this case, although there is no direct evidence supporting the link between insulin and treatment for depression, more and more researches support this hypothesis." (PMID 32281722, 2020). "These evidences show the effect of excessive insulin on CRH may indicate its negative impact on depression." (PMID 32281722, 2020). "Therefore, brain insulin signaling dysfunction could impair the HPA axis normal response to stress, possibly facilitating the development of depression for example." (PMID 31349552, 2019). "Interestingly, presence of depression neither depended on age, duration of illness, insulin dose, or lipodystrophies." (PMID 29529063, 2018). "Negative emotions such depression also had an impact on insulin use." (PMID 29788908, 2018). "Furthermore, the severity of the disease and the use of medications for depression (insulin and/or oral) are not collected in the database." (PMID 25706646, 2015). "Taking these factors into account, five-and-a-half years of follow-up might not have been long enough to detect any meaningful differences in time to insulin initiation between those with and without depression." (PMID 24223860, 2013). "Similarly, patients treated with oral medications and/or insulin were less likely to have been screened for depression than those not on pharmaceutical treatment for glycaemic control." (PMID 23738766, 2013). "Higher scores on the total PAID and its subscales scores were significantly associated with higher levels of depression (CES-D) scores and a more negative appraisal of insulin therapy (ITAS scores), and also with higher ratings of having problems with the regulation of blood glucose levels." (PMID 22195273, 2011). "The subgroup analyses on the medications (pioglitazone, metformin and insulin) and diagnosis (MDD and bipolar depression) did not detect any clinical relevance of heterogeneity (Figure A1)." (PMID 38398483, 2024). "Compared with those who were not on insulin treatment, those on insulin treatment were more likely to have advanced T2DM with less endogenous insulin, increasing their susceptibility to metabolic dysregulation; hence, they were more vulnerable to develop depression." (PMID 36918821, 2023). "Furthermore, lack of proper central insulin signaling would result in dysfunctional hippocampal neurogenesis, which may play a role in the pathophysiology of depression and T2DM." (PMID 32971941, 2020). "However, in a double-blind study examining the effect of intranasal insulin administration on cognitive function and mood symptoms in patients with treatment-resistant depression, intranasal insulin did not result in statistically significant improvement in overall mood or cognition." (PMID 32971941, 2020).
depression (continued). "Furthermore, a compensatory increase in insulin release, manifested by increased early-phase insulin release and total insulin secretion during the OGTT although not significantly, was observed to maintain fasting and 2-h glucose levels within the normal range in patients with depression." (PMID 27274905, 2016). "We observed that patients without depression and no longer meeting PTSD criteria were statistically significantly less likely to start insulin." (PMID 39136942, 2024). "A history of anxiety/depression requiring medication prior to or during pregnancy was common i.e. 35% of the non-GDM group, 15% of the GDM-Diet group and 60% of the GDM-Insulin group." (PMID 36733299, 2023). "Although depression scores (EDS) tended to be higher in women with GDM (both diet and insulin-treated) than women in the non-GDM group at both time points, these differences were not statistically significant." (PMID 36733299, 2023). "A significant negative correlation is found between HRQoL and insulin daily dose(P = 0.022), HbA1C(P < 0.001), average SMBG(P < 0.001) and MINI-KID depression scale(P < 0.001)." (PMID 35690827, 2022). "Age, BMI, WC, acne, T, FAI, fasting insulin, FPG, and HOMA-IR were significantly different (P < 0.05) when comparing participants with depression (SDS-SS ≥ 53) to those without (SDS-SS < 53)." (PMID 34744814, 2021). "In the CM group, reduced insulin sensitivity (measured by the Matsuda index and HOMA-IR), independent of age, sex, race, education, and depression, was observed." (PMID 28713332, 2017). "In non-diabetic patients with depression, phenelzine lowers fasting blood glucose, while in various obesogenic mouse models, it reduces hepatic MDA, improves insulin sensitivity, increases plasma insulin, maintains normoglycemia, and decreases inflammation." (PMID 41384022, 2025). "However, age group in years, nationality, BMI, method of insulin administration, and history of DKA were not significant parameters when compared with depression (p > 0.05)." (PMID 34770232, 2021). "Lack of insulin action and oxidative stress changes the composition and action of many tissues and organs, which results in the development of depression among DT2 patients and DT2 in people suffering from depression." (PMID 30026880, 2018).
endothelial dysfunction (588 papers, 2004 to 2026). In vascular diseases, endothelial dysfunction is a systemic pathological state of the endothelium (the inner lining of blood vessels) and can be broadly defined as an imbalance between vasodilating and vasoconstricting substances produced by (or acting on) the endothelium. "Reduced Cav-1 expression has been associated with endothelial dysfunction and impaired insulin signaling in neurodegenerative diseases." (PMID 41280311, 2025). "Obesity-associated endothelial dysfunction delays the action of insulin in increasing microvascular blood volume (MBV) and reduces systemic glucose uptake." (PMID 39503770, 2025). "Among them, chronic inflammation, oxidative stress, insulin resistance, and blood flow obstruction caused by endothelial dysfunction and calcification of the skeletal muscle vasculature are all regarded as possible causes." (PMID 40034988, 2025). "Physiologically, endothelial dysfunction and vascular remodeling in the pulmonary circulation are caused by hyperglycemia-induced oxidative stress, inflammation, and dysregulated insulin signaling pathways." (PMID 39050565, 2024). "NAFLD and CVD both share several common metabolic risk factors such as genetics, systemic inflammation, endothelial dysfunction, hepatic insulin resistance, adipose tissue dysfunction, oxidative stress, and lipid metabolism." (PMID 38730426, 2024). "The present study showed that systemic endothelial dysfunction, detectable as impaired responses to insulin and acetylcholine, associates with increased risk of HFpEF in women with T2D." (PMID 37658327, 2023). "TZT improves endothelial dysfunction (ED) and associated inflammatory changes through modulation of glucose homeostasis, insulin sensitivity, and pro-inflammatory biomarkers release." (PMID 37208555, 2023). "Effectiveness of a MUFA-enriched diet to improve insulin sensitivity and associated cardiometabolic risk, as well as improve blood lipids and systemic inflammatory responses and endothelial dysfunction." (PMID 36937354, 2023). "TZT improves endothelial dysfunction (ED) and associated inflammatory changes through modulation of glucose homeostasis, insulin sensitivity, and release of pro-inflammatory biomarkers." (PMID 37208555, 2023). "For example, various studies linked chronic phosphodiesterase 5 inhibition with enhanced insulin sensitivity and attenuated endothelial dysfunction." (PMID 37460929, 2023). "CRP from liver synthesis plays an important role in the inflammatory processes associated with MetS, insulin sensitivity, endothelial dysfunction, and fibrinolysis failure." (PMID 38140392, 2023). "Endothelial dysfunction and decreased nitric oxide synthase activity are also caused by impaired insulin signaling, resulting in systemic vasoconstriction." (PMID 35370984, 2022). "Insulin-resistant states are associated with metabolic abnormalities that include glucotoxicity, lipotoxicity and inflammation, and which also lead to endothelial dysfunction." (PMID 34440804, 2021). "A previous study indicated that aging caused significant endothelial dysfunction, such as the decreased arterial vasorelaxing responses to insulin, in the Sprague–Dawley (SD) rats." (PMID 34203897, 2021). "We also observed that EDIH was more strongly related to biomarkers of insulin response, showed about equal magnitude of associations with biomarkers of inflammation and endothelial dysfunction, and showed weaker associations with lipids, compared to EDIP." (PMID 34616762, 2021). "ER stress response by itself can result in endothelial dysfunction, a hallmark of cardiovascular disease, through various cellular mechanisms including apoptosis, insulin resistance, inflammation and oxidative stress." (PMID 33053883, 2020). "ER stress response by itself can result in endothelial dysfunction through various underlying molecular mechanisms including apoptosis, insulin resistance, inflammation, autophagy and oxidative stress." (PMID 33053883, 2020).
endothelial dysfunction (continued). "Inflammation and oxidative stress are associated with endothelial dysfunction and vascular hypertrophy, in which microvascular endothelium-dependent vasodilation is impaired in response to vasodilators such as insulin." (PMID 32685208, 2020). "Other studies showed a potential association between exogenously administered insulin and impaired endothelial dysfunction." (PMID 30819191, 2019). "Potentially, insulin counteracts the vasoconstriction caused by endothelial dysfunction and increased sympathetic activity known to be present in albuminuric patients with T2D." (PMID 31119456, 2019). "This supports the role of exercise as a treatment in the improvement of several cardiovascular risk factors in PCOS, including abdominal adiposity, insulin sensitivity, endothelial dysfunction and androgen profile." (PMID 31890686, 2019). "IFNγ then possibly induces insulin insensitivity seen as higher insulin to be an early marker of endothelial dysfunction and increased susceptibility to CVD later in life." (PMID 30138332, 2018). "The association between reduced insulin signaling and endothelial dysfunction is well established and is characterized by diminished endothelial NO generation and oxidative stress resulting from increased superoxide production." (PMID 29796592, 2018). "An increasing number of studies confirm that increased systemic oxidative stress in overweight or obese patients directly impacts the insulin sensitivity of metabolic organs, promotes inflammation, alters lipid metabolism, and causes endothelial dysfunction." (PMID 28484502, 2017). "The decreased ADMA level in GDM patients seems to be preventive in the limitation of NO synthesis caused by the impaired insulin action and the endothelial dysfunction." (PMID 26981539, 2016). "Endothelial dysfunction was correlated with individual metabolic risk components, but more strongly with clustering of the components under a condition with low insulin sensitivity." (PMID 27188597, 2016). "Particulate matter concentration is influenced by ETS and has also been shown to cause adipose tissue inflammation, endothelial dysfunction and impaired insulin signalling in animal models." (PMID 25253088, 2014). "Under pathological conditions, proinflammatory factors cause an impairment in this particular insulin-signalling pathway in the endothelium, which promotes endothelial dysfunction." (PMID 22709426, 2012). "In turn, endothelial dysfunction is both a cause and a consequence of the metabolic abnormalities typical of insulin resistant states." (PMID 21135801, 2010). "Oxidative stress, alterations in the insulin signaling, and NO signaling have been associated with endothelial dysfunction." (PMID 18335025, 2008). "The association between high postprandial triglyceride and insulin levels after a mixed meal with high CAMs is presumably indicating an early stage of endothelial dysfunction." (PMID 18761738, 2008). "In contrast, in non-hypertensive individuals, visceral fat may play a more direct role in increasing stroke risk through mechanisms such as insulin resistance, chronic inflammation, and endothelial dysfunction." (PMID 40013043, 2025). "We previously reported that these individuals have endothelial dysfunction but whether this associates with improved or impaired insulin sensitivity is unknown." (PMID 39503770, 2025). "Both entities share overlapping pathophysiologic mechanisms—including insulin resistance, oxidative stress, and endothelial dysfunction—that underlie adverse pregnancy outcomes; therefore, their combined analysis was considered appropriate for this initial investigation." (PMID 41275113, 2025). "Endothelial dysfunction caused by high insulin levels is hypothesized to act as a link between metabolic disorders and cardiovascular disease development." (PMID 39661465, 2024). "Few reports have mentioned that insulin-treated pregnant women may face a low risk of fetoplacental endothelial dysfunction." (PMID 37946069, 2024).